ENSG00000252461
Gene: Small nucleolar RNA gene on chromosome 16 (28,881,480 to 28,881,607, reverse strand). Ensembl gene ENSG00000252461.
Homologues: Paralogues in human: SNORA17B (62% identical), SNORA17A (48% identical).